EPN3 (epsin 3)
Synonyms: FLJ20778; MGC129899
Tractability: Antibody: its Gene Ontology location is reachable by antibodies, with medium confidence. PROTAC: ubiquitination databases record sites on it.
Gene: Protein-coding gene on chromosome 17 (50,532,548 to 50,543,750, forward strand). Ensembl gene ENSG00000049283.
Subcellular location: Cytoplasm; Cytoplasm, perinuclear region; Cytoplasmic vesicle, clathrin-coated vesicle; Nucleus
Subcellular location (Human Protein Atlas): Vesicles; Nucleoplasm
Gene Ontology:
Molecular function: protein binding; phospholipid binding; EH domain binding
Biological process: endocytosis
Cellular component: clathrin-coated vesicle; cytoplasmic side of plasma membrane; extracellular exosome; nucleus; perinuclear region of cytoplasm; clathrin vesicle coat; clathrin-coated pit; cytoplasm
Genetic constraint (gnomAD): Loss-of-function variants: 54 observed, 54.17 expected, observed/expected ratio (o/e) 1, 90% interval 0.8 to 1.25. The synonymous counts are far from expectation, so gnomAD's model fits this gene poorly and the ratio says little. Missense variants: 927 observed, 838.75 expected, observed/expected ratio (o/e) 1.11, 90% interval 1.05 to 1.17. Synonymous variants: 449 observed, 373.07 expected, observed/expected ratio (o/e) 1.2, 90% interval 1.11 to 1.3.
Homologues: Orthologues: chimpanzee EPN3 (99% identical), macaque EPN3 (97% identical), dog EPN3 (90% identical), rat Epn3 (87% identical), mouse Epn3 (87% identical), pig EPN3 (84% identical), guinea pig EPN3 (84% identical), rabbit EPN3 (84% identical), zebrafish epn3a (47% identical), zebrafish epn3b (46% identical), tropical clawed frog epn3 (43% identical), Drosophila melanogaster lqf (36% identical), and 1 more. Paralogues in human: EPN2 (45% identical), EPN1 (44% identical), ENTHD1 (24% identical), CLINT1 (23% identical), MYCBPAP (18% identical).
Diseases named in the same sentence as EPN3 in open-access papers:
EPN3 is named in the same sentence as 14 diseases in open-access papers, as found by Europe PMC text mining. Sharing a sentence is not in itself a finding about the gene and the disease. The quoted sentences say what the papers report.
breast carcinoma (10 papers, 2011 to 2025). "Here, we show that EPN3 is overexpressed in ~40% of breast cancers (BCs) and that its overexpression (associated with gene amplification in ~25% of the overexpressing cases) is an independent predictor of distant metastasis." (PMID 32541686, 2020). "Four of the ten late-type genes, the ribosome-related factors EIF4B, RPL5, RPL3, and the tumor angiogenesis modifier EPN3 were significantly associated with MFS in the late period also in a meta-analysis of tamoxifen-treated breast cancer cohorts." (PMID 27926932, 2016). "EPN3 has been demonstrated to influence tumour progression in breast cancer, oral squamous cell carcinoma, and glioblastoma." (PMID 39910656, 2025). "In upregulated mRNAs in breast cancer tissue, EPN3 was up-expressed as the cancer progressed, and ZNF8 was down-expressed as the cancer progressed." (PMID 36294892, 2022). "Among the 20 identified DE mRNAs, EPN3 expression was upregulated in breast cancer tissues compared to that in normal tissues and was upregulated as the histopathological grade of breast cancer increased." (PMID 36294892, 2022). "Here, we report that Epsin 3 (EPN3) is an oncogene with prognostic and therapeutic relevance in breast cancer." (PMID 32541686, 2020). "Additionally, we observed elevated expression of EPN3 in various epithelial malignancies including breast cancer (BRCA) and colon adenocarcinoma (COAD)." (PMID 39910656, 2025). "Although EPN3 was not included in our initial set of breast cancer-associated genes, previous studies have identified it as an oncogene involved in breast cancer by regulating epithelial-mesenchymal transition, playing a crucial role in metastasis." (PMID 41266338, 2025). "Furthermore, EPN3 has been explored as a potential therapeutic target due to its role in regulating apoptosis in breast cancer cells." (PMID 41266338, 2025). "While reduced expression of EPN3 may seem counterintuitive given its reported oncogenic overexpression in breast cancer, this could reflect transcript-specific or cell-type-dependent regulation, warranting further investigation." (PMID 41266338, 2025). "In addition, EPN3 was upregulated in other breast cancer-related studies, similar to this study, but was downregulated in gastric cancer and upregulated in glioblastoma, with the opposite results." (PMID 36294892, 2022). "EPN3 expression is upregulated in wounded epithelial tissues and it can drive breast tumorigenesis by increasing E-cadherin endocytosis, EPN3 is overexpressed in 40% of breast cancers and its overexpression is an independent predictor of distant metastasis.." (PMID 33842346, 2021). "Here, the authors report the oncogenic role of Epsin3 (EPN3) in breast cancer, and show EPN3 to drive tumorigenesis through induction of a partial epithelial mesenchymal transition state and a TGFβ-dependent regulatory loop that promotes cellular plasticity and invasive behaviour." (PMID 32541686, 2020). "One late-type gene (EPN3) was significantly associated with shorter OS, and two late-type genes (RPL3, EIF4B) with longer OS, in more than one cohort, in agreement with findings in breast cancer." (PMID 27926932, 2016). "Finally, four genes (PTPN2, MTSS1, EPN3, and C17ORF37) are associated with cell migration and adhesion and/or poor prognosis of breast cancer." (PMID 21339811, 2011). "We found nominal evidence of association with breast cancer overall for LoF variants in three genes (ZFAND1, TMEM206/PACC1, and TYRO3), with ER-negative breast cancer in two genes, DNAH11 and PARP2, and with ER-positive disease in four genes LAMC3, MTMR11, EPN3, and SLC22A10." (PMID 35884425, 2022). "Of these twenty, three showed evidence of association with LoF variants for overall breast cancer (ZFAND1, TYRO3, TMEM206/PACC1), and a further six with breast cancer subtypes (DNAH11, PARP2, LAMC3, MTMR11, EPN3, SLC22A10)." (PMID 35884425, 2022).
breast carcinoma (continued). "Multiple other genes from the driver subnetworks, including GRB2, MED1, MED24, and EPN3 are also located in the proximity of the same amplicon (between 17q12–25), underscoring the significance of this chromosomal region in HER2+ breast cancer." (PMID 22343619, 2012). "However, among the DE mRNAs whose expressions were upregulated in breast cancer tissues, TOMM40 was highly expressed in TNBC compared to that seen in other molecular subtypes, and EPN3 was expressed lower in TNBC than in other molecular subtypes." (PMID 36294892, 2022). "In breast cancer, Epsin 3 (EPN3) can enhance E-cadherin endocytosis, activate β-catenin/TCF4-mediated EMT and promote the autocrine loop mediated by TGFβ, and ultimately promote metastasis of breast cancer cell." (PMID 34034721, 2021). "However, EPN3 expression patterns could not be compared because there are very few studies related to breast cancer." (PMID 36294892, 2022). "EPN3-induced partial EMT is instrumental for the transition from in situ to invasive breast carcinoma, and, accordingly, high EPN3 levels are detected at the invasive front of human breast cancers and independently predict metastatic rather than loco-regional recurrence." (PMID 32541686, 2020).
glioblastoma (2 papers, 2021 to 2022). The most malignant astrocytic tumor (WHO grade IV). "EPN3 expression has been reported to be upregulated in high-grade tissues compared to that in low-grade tissues in glioblastoma." (PMID 36294892, 2022). "Experimental data further indicate that EPN3 may promote the migration and invasion of glioblastoma cells." (PMID 33430387, 2021). "For example, in glioblastoma (and possibly other tumor types), the glycoprotein Epsin3 (EPN3) may be related to Notch and WNT/β-catenin signaling pathways, and helps to induce EMT in glioblastoma cells after activating SLUG, TWIST, and ZEB1, but not Snail1 or ZEB2." (PMID 33430387, 2021).
lung carcinoma (2 papers, 2016 to 2025). "To elucidate the mechanism by which EPN3 regulates lung cancer growth and metastasis, we performed RNA-seq in A549 cells with stable EPN3 knockdown." (PMID 39910656, 2025). "Collectively, these findings indicate that EPN3 is necessary for the proliferation of lung cancer cells." (PMID 39910656, 2025). "On the other hand high expression of epsin (EPN3) with its well-established role in tumor angiogenesis, conferring worse prognosis in breast and lung cancer, is of high clinical relevance considering the ongoing development of epsin antagonizing therapies." (PMID 27926932, 2016).
chronic hepatitis B (1 paper, 2022). "And in vivo, by mining the microarray data of chronic hepatitis B (CHB) liver (GSE83148) and HBV-infected human-liver chimeric mice (GSE52752), we found that EPN3 was highly expressed in the HBV-infected liver, compared to the uninfected controls." (PMID 35935763, 2022).
ependymoma (1 paper, 2023). A WHO grade II, slow growing tumor of children and young adults, usually located intraventricularly. "Here, we performed more a detailed analysis by comparing different culture conditions of ependymoma, focusing on two patients (EPN1 and EPN3)." (PMID 37508868, 2023).
non-small cell lung carcinoma (1 paper, 2016). A group of at least three distinct histological types of lung cancer, including non-small cell squamous cell carcinoma, adenocarcinoma, and large cell carcinoma. "In contrast, only one late-type gene (EPN3) showed consistent survival associations in more than one cohort in the other cancer types, being associated with worse outcome in two non-small cell lung cancer cohorts." (PMID 27926932, 2016).
tumor (8 papers, 2016 to 2025). "EPN3 silencing resulted in a decreased number of Ki67-positive cells in the xenograft mouse tumours." (PMID 39910656, 2025). "After 21 days, the growth rate of tumours was significantly lower in the mice injected with EPN3-knockdown cells than in those injected with A549-shNC cells." (PMID 39910656, 2025). "In this study, we present novel evidence demonstrating that EPN3 affects tumour progression through interacting with EGFR and inhibiting the lysosomal degradation pathway of EGFR." (PMID 39910656, 2025). "The PCA plot showed the close clustering of EPN3 in vitro samples with the primary tumor tissue; however, it also showed clear separation from EPN1 in vitro samples." (PMID 37508868, 2023). "We cannot refer here to a plethora of newer reports related to EPN3/Epsin functions, e.g., in podocyte formation, invasiveness, and tumor cell plasticity." (PMID 33430387, 2021). "The tumor tissues derived from basal, Her2, LumA, and LumB breast tissues were not significantly different between normal and tumor ones; for EPN3: the expression level is displayed in the box plot." (PMID 34572798, 2021). "On the other hand, the analysis showed that EPN3 did not present a significant risk in tumor breast tissues derived from basal, Her2, LumA (LumA), and LumB (LumB) cell types." (PMID 34572798, 2021). "EPN3 belongs to the epsin family of endocytic adaptor proteins, originally described to be involved in clathrin-mediated internalization of cell surface receptors and lately reported to play a role in angiogenesis as well as tumor cell migration and invasion." (PMID 27926932, 2016). "Moreover, the increased EGFR protein levels in the tumour tissues of NSCLC patients and the decreased EGFR protein levels in xenograft tumours following EPN3 knockdown suggest that the ErbB signalling pathway may play a role in A549 cell proliferation and differentiation after EPN3 knockdown." (PMID 39910656, 2025). "SPDEF, TRIM3, HSPB1, SPINT1, EPN3, and LRFN2 were significantly highly expressed in the HER2-positive type than in TNBC (p < 0.05), as the HER2-positive type is reported to have a larger tumor size and higher stage." (PMID 36428562, 2022). "The two alterations, however, seem to influence the tumor phenotype independently, as supported by finding that ~50% of the EPN3-amplified cases do not show ERBB2 amplification." (PMID 32541686, 2020). "Indeed, EPN3 silencing in MCF10DCIS.com cells not only reduced tumor growth, but importantly, also reduced the p63/α-SMA-positive area of tumors during IBC progression over time, when normalized on tumor size." (PMID 32541686, 2020). "While a potential role in regulating tumor angiogenesis has been proposed for EPN1 and EPN251,52, our results show that EPN1 overexpression does not phenocopy any of the investigated EPN3 effects, thereby pointing to a specific modality of transformation by EPN3, at least in BC." (PMID 32541686, 2020).
cancer (6 papers, 2012 to 2025). A tumor composed of atypical neoplastic, often pleomorphic cells that invade other tissues. "In this study, consistent with previous reports, we identified EPN3, a member of the adaptor protein family involved in receptor endocytosis, as a cancer marker in NSCLC, and its upregulation was correlated with NSCLC progression." (PMID 39910656, 2025). "Given the link between EPN3 and the invasive behavior of cancer cells, we aimed to establish the clinical relevance of EPN3 to BC metastasis." (PMID 32541686, 2020). "In addition, EPN3 has been reported to enhance the migration and invasion of cancer cells." (PMID 36294892, 2022).
EPN3 also shares sentences with these, for which no sentence is quoted: colon adenocarcinoma (1 paper); gastric cancer (1); glomerulosclerosis (1); infection (1); invasive breast carcinoma (1); kidney failure (1).